CD38 (CD38 molecule)
Diseases named in the same sentence as CD38 in open-access papers (continued):
Sharing a sentence is not in itself a finding about the gene and the disease.
pulmonary fibrosis (6 papers, 2018 to 2025). Chronic progressive interstitial lung disorder characterized by the replacement of the lung tissue by connective tissue, leading to progressive dyspnea, respiratory failure, or right heart failure. "CD38 antigen receptor membrane‐modified MSC‐derived extracellular vesicle (CD38‐ARM‐MSC‐EV) associated technology is a promising agent with high clinical potential against pulmonary fibrosis." (PMID 39665319, 2025). "Here we demonstrate here that selectively targeting the CD38 NADase ectoenzyme with the catalytically inhibitory heavy-chain monoclonal antibody can mitigate skin and lung fibrosis in mice." (PMID 38086958, 2023). "CD38 levels were markedly elevated in the lungs from patients with idiopathic pulmonary fibrosis (IPF), and genetically targeting CD38 in mice attenuated bleomycin-induced lung fibrosis." (PMID 38086958, 2023). "Concentrations of CD38+ memory CD27− B-cells, IgA+ memory CD27+ B-cells, and IgM+ and IgD+ B-cells were significantly higher in patients affected with either FPF or HPS pulmonary fibrosis compared with unaffected controls." (PMID 29445374, 2018). "We further analyzed if the non-canonical adenosinergic CD38/CD203a pathway might contribute to radiation-induced lung fibrosis." (PMID 33194619, 2020). "Percentages of CD38+ memory CD27− B-cells, IgA+ memory CD27+ B-cells, IgM+ and IgD+ B-cells, and CD39+ T helper cells were significantly higher whereas CD39− T helper cells were significantly lower in patients with either FPF or HPS pulmonary fibrosis compared with URels." (PMID 29445374, 2018).
sarcoidosis (6 papers, 2020 to 2024). Sarcoidosis is a multisystemic disorder of unknown cause characterized by the formation of immune granulomas in involved organs. "Recent studies described that patients with sarcoidosis had reduced levels of peripheral blood “naïve” IgD + CD38– and memory IgD–CD38+ and IgD–CD38– B cell subsets, while activated IgD + CD38+ and IgD + CD38++ were increased." (PMID 38179278, 2023). "Remarkably, the pattern of peripheral B cell distribution to different subsets, based on IgD vs. CD38 as well as IgD vs. CD27 co-expression in sarcoidosis patients according to available data was very similar to that reported for SS patients." (PMID 31974463, 2020). "In the meantime, it was found that the proportion of Bregs (CD19+CD24+CD38+) in the peripheral blood of patients with active sarcoidosis was significantly higher when compared to patients with stable sarcoidosis and healthy controls." (PMID 32508842, 2020). "Foremost, in peripheral blood samples from sarcoidosis patients we observed higher frequencies of CD24+++ CD38+++ B cells compared with those in matched HC." (PMID 31974463, 2020). "Both CD3+CD4+CD38+ and CD38+ B cell subsets were found to be elevated in BAL as markers of an acute immune response in sarcoidosis patients." (PMID 36203777, 2022). "In preliminary studies, we have shown that “naive” activated B-lymphocytes (Bm2) with IgD+CD38+ phenotype and the general subpopulation of “naive” B-lymphocytes with CD5−CD27− phenotype was increased in the circulation in patients with sarcoidosis relative to the values of the control group." (PMID 39410592, 2024). "Moreover, we found that in sarcoidosis patients there are increased levels of B cell subsets, which were previously shown to display regulatory capacities (CD24+++ CD38+++ and CD5 + CD27−)." (PMID 31974463, 2020).
Cerebral ischemia (5 papers, 2011 to 2024). Restriction of arterial blood supply to the brain associated with insufficient oxygenation to support the metabolic requirements of the tissue. "We show that the local expression of the chemokine MCP-1 was attenuated in CD38-deficient mice compared with wildtype mice after focal cerebral ischemia and reperfusion." (PMID 21625615, 2011). "Further, using an in vitro model of brain ischemia, we demonstrated CD38 inhibition reduces clustering of GABAergic synaptic components via a TRPM2-dependent pathway." (PMID 40822706, 2024). "Once again, mice were subjected to 60 min focal cerebral ischemia, and 5 days later, intracerebroventricular infusion of control siRNA or CD38 siRNA was performed." (PMID 38007588, 2023). "An up-regulation of CD38 expression was observed in macrophages and CD8+ cells after focal cerebral ischemia in wildtype mice, whereas CD38 expression was unchanged in microglia." (PMID 21625615, 2011). "Focal cerebral ischemia was induced for one hour with the intraluminal filament technique in wildtype and CD38−/− animals." (PMID 21625615, 2011). "Therefore, we analyzed CD38 expression on immune cells accumulating in the ischemic brain 3, 24 and 72 hours after focal cerebral ischemia induction in CD38−/− and wildtype mice." (PMID 21625615, 2011). "In addition, CD38 may play a role in trans-endothelial migration across the BBB via its interaction with CD31 whereby CD38 was found to be essential for T cell infiltration in a mouse model of cerebral ischemia." (PMID 36294327, 2022). "Therefore, CD38 might prove to be a therapeutic target to modulate the inflammatory mechanisms after cerebral ischemia." (PMID 21625615, 2011). "While CD38 is primarily known for its role in NAD depletion in aging and tumorigenesis, several studies have also highlighted its relevance in brain ischemia." (PMID 40822706, 2024). "However, HLA-DR− CD38− Tregs were significantly reduced during EBI phase in patients with cerebral ischemia (CI) compared to those without CI." (PMID 34244562, 2021).
chronic obstructive pulmonary disease (5 papers, 2019 to 2025). A chronic and progressive lung disorder characterized by the loss of elasticity of the bronchial tree and the air sacs, destruction of the air sacs wall, thickening of the bronchial wall, and mucous accumulation in the bronchial tree. "Collectively, our findings provide unambiguous evidence for a non-canonical NAD+-dependent adenosinergic pathway in the lungs, implicating CD38 as a major contributor to this process with potential therapeutic value in chronic obstructive pulmonary diseases." (PMID 33120985, 2020). "Eligibility criteria varied across pivotal anti-CD38-based trials in RRMM, with some studies excluding patients with chronic obstructive pulmonary disease (COPD) or cardiovascular impairments." (PMID 40786241, 2025). "Additionally, studies have also linked CD38+ macrophages to chronic obstructive pulmonary disease (COPD), though no mechanistic studies have yet provided clear data as to the functional role of CD38 in this chronic inflammatory condition." (PMID 31878283, 2019).
Cirrhosis (5 papers, 2020 to 2025). A chronic disorder of the liver in which liver tissue becomes scarred and is partially replaced by regenerative nodules and fibrotic tissue resulting in loss of liver function. "This study underscores the critical roles of TBil, CD38, and IL-22 in cirrhosis development among AIH patients and validates the diagnostic and prognostic significance of TSP-1, Gal-3, Cys-C, AIb, and PA in compensated cirrhosis." (PMID 40417691, 2025). "Multivariate logistic regression identified elevated TBil and reduced CD38 and IL-22 levels were associated with increased cirrhosis risk." (PMID 40417691, 2025). "Multivariate logistic regression analysis identified TBil, CD38, and IL-22 as independent factors influencing cirrhosis development in AIH patients." (PMID 40417691, 2025). "Combined detection of TBil, CD38, and IL-22 levels demonstrated high sensitivity and specificity for predicting cirrhosis development in AIH patients, highlighting their potential as reliable biomarkers for early identification and risk assessment." (PMID 40417691, 2025). "We also noticed a marked elevation of CD27+CD38++ plasma cells in patients with ACLF (p < 0.05 for ACLF vs. cirrhosis and for ACLF vs. HC)." (PMID 36505417, 2022). "However, TBil levels were significantly higher, and CD38 and IL-22 levels were significantly lower in the cirrhosis group." (PMID 40417691, 2025). "We found that the ACLF liver harbored reduced fraction of naïve B cells and elevated percentage of CD27+CD21− activated memory B cells (AM), CD27−CD21− atypical memory B cells (atMBC), CD27+IgD−IgM+(IgM+ memory B cells), and CD27+CD38++ plasma cells than cirrhosis and healthy controls." (PMID 36505417, 2022). "Among the Breg subtypes, the PBC- and cirrhosis-associated cluster most closely represented B10 cells, due to the lack of CD38 and high expression of IgD34." (PMID 32724082, 2020). "To examine B cell phenotypes in D-LC caused by HBV, we performed flow cytometry using a panel of 11 markers (CD19, CD10, CD38, IgD, CD21, CD27, CCR7, CXCR3, CXCR4, CXCR5, and IL-21R) and demonstrated the changes of B cell subsets for the first time in HBV-associated advanced cirrhosis." (PMID 34248941, 2021).
HCMV infection (5 papers, 2005 to 2024). "Together, these data show that CD38 expression on CMV-specific CD8+ T cells increases in mice enduring CMV infection under immunosuppressive conditions, which associates with an increased mitochondrial mass and reduced expression of ATP5a." (PMID 38954588, 2024). "Mouse model of CMV infection confirms an increased CD38 expression on CMV-specific CD8+ T cells and association with metabolic alterations." (PMID 38954588, 2024). "Kidney transplant recipients who are unable to control cytomegalovirus infection have dysfunctional CD8+ T cells that can be metabolically reinvigorated by targeting the NADase CD38." (PMID 38954588, 2024). "All together, we conclude that CD38 expression is particularly elevated in the setting of CMV infection." (PMID 38954588, 2024). "Together, these data underscore that active CMV infection in mice and humans lead to a particular increase of CD38 expression by virus-reactive CD8+ T cells." (PMID 38954588, 2024). "Since CD38 also mediated NAD metabolism, these CD38-KO iPSC-NK cells have features similar to so-called adaptive NK cells that arise after cytomegalovirus infection." (PMID 35185932, 2022). "Persistent CMV infection drove high expression of CD38 on antigen-specific CD8+ T cells." (PMID 38954588, 2024). "However, there are differences between subpopulations of progenitor cells: CD34+/CD38− cells support an HCMV infection with the hallmarks of latency, but a subset of CD34+/CD38− cells expressing a stem cell phenotype (lineage−/Thy-1+) support productive HCMV infection." (PMID 32296651, 2020). "Further studies of HCMV infection in CD34 cells will help in defining whether CD34+ infected cells undergo cell differentiation by increased expression of other markers such as CD33, CD38, HLA-DR or cytokines." (PMID 15673469, 2005).
hepatitis C (5 papers, 2014 to 2025). "In chronic viral infections like HIV and hepatitis C, the immune exhaustion exhibited by CD38+HLA-DR+ T cells has been observed, and is manifested by diminished proliferation and effector function." (PMID 40370439, 2025). "Persistent sufferers of hepatitis C are bombarded by heavily cytotoxic CD38+HLA-DR+CD8+ T cells, which elicit liver damage." (PMID 38474367, 2024). "It has been proposed that CD8+ cells expressing HLA-DR without CD38 are preferentially generated in response to low antigenic stimulation and that by retaining good effector function, may play a role in suppressing HIV replication in elite controllers, as well as clearing hepatitis C infection." (PMID 26498496, 2015).
inflammatory bowel disease (5 papers, 2015 to 2024). A spectrum of small and large bowel inflammatory diseases of unknown etiology. "Proteomic analyses of intestinal tissues from healthy controls and patients with inflammatory bowel disease have revealed upregulation of CD38, with heightened CD38 protein expression observed in inflamed areas of the colonic mucosa in patients with ulcerative colitis." (PMID 39620226, 2024). "CD38bright CD8+ T cells can predict acute graft-versus-host disease, phenotypic changes in CD38+ CD4+ T cells can predict the severity of inflammatory bowel disease, and CD38 expression in CD4+, CD8+, or CD25+ T cells is significantly higher in SLE patients than in healthy controls." (PMID 37445926, 2023).
Listeria infection (5 papers, 2018 to 2025). "The inability of CD38 deficient macrophages to control Listeria infection in macrophages is due to impaired phagocytosis, as CD38 deficient-murine macrophages maintain their ability to kill L. monocytogenes." (PMID 33329591, 2020). "Interestingly, genetic deletion of CD38 resulted in increased accumulation of inflammatory monocytes in the liver but not in the spleen and was associated with higher susceptibility to listeria infection, as observed during genetic deletion of Ccr2." (PMID 36010615, 2022). "In contrast, monocytes from the listeria infection model expressed M1-related transcription factors (e.g., Irf2, Mndal, Ifi204) and showed higher expression of CD38, CD74, and CD86, as well as higher ROS production." (PMID 36010615, 2022). "In vivo, CD38+/hi macrophages are also induced during infectious and sterile inflammatory processes such as murine models of Listeria infection, LPS-induced sepsis, DSS-induced colitis, and focal ischemia." (PMID 30042766, 2018). "More recently, CD38 has been found to be necessary for resistance to Listeria infections via NAD depletion and actin cytoskeleton modulation." (PMID 30042766, 2018). "Similarly, the role of CD38 in controlling Listeria monocytogenes infection appears to stem from its role in phagocytic function." (PMID 33329591, 2020).
liver cancer (5 papers, 2020 to 2024). An epithelial or non-epithelial malignant neoplasm that arises from the liver. "Furthermore, isatuximab-treated NK92V/V cells showed significantly increased cytolytic activity against CD38− liver cancer JHH6 cells when compared with IgG1-treated NK cells." (PMID 32922390, 2020).
Lymphadenopathy (5 papers, 2016 to 2025). Enlargement (swelling) of a lymph node. "Increased levels of CD49d (α4) expression can be associated with inferior prognosis in IgHV-UM and CD38 expressing cases and the occurrence of trisomy 12 likely associating with the appearance of lymphadenopathies." (PMID 27374180, 2016). "These are assisted by several clonal factors that potentiate migratory responses favoring clinical lymphadenopathy and poor outcome, including the presence of certain adverse prognostic factors such as CD38, ZAP70, CD49d, trisomy 12, NOTCH1 mutations, or un-mutated IGHV." (PMID 33841445, 2021).
osteoarthritis (5 papers, 2013 to 2024). A noninflammatory degenerative joint disease occurring chiefly in older persons, characterized by degeneration of the articular cartilage, hypertrophy of bone at the margins and changes in the synovial membrane. "The changes in expression of anabolic and catabolic genes implicate CD38 as an effective target for altered homeostasis of cartilage matrix in the treatment of osteoarthritis." (PMID 35441488, 2022). "Notable fractions of CD20+ and CD38+ cells appeared in a subset of osteoarthritis samples, and increased further in early, rheumatoid and chronic septic arthritis." (PMID 23951325, 2013). "Regulating the CD38 expression may be a therapeutic approach to protect the cartilage against osteoarthritis." (PMID 35441488, 2022). "Serial synovial tissue sections from all RA patients, 13 osteoarthritis, and 10 orthopedic arthropathies patients were stained with hematoxylin and eosin and immunohistochemically for MMP-3, CD3, CD20, CD38, CD68, and CD15." (PMID 25147433, 2014).
Parkinson disease (5 papers, 2019 to 2026). A progressive degenerative disorder of the central nervous system characterized by loss of dopamine producing neurons in the substantia nigra and the presence of Lewy bodies in the substantia nigra and locus coeruleus. "CD38 is also implicated in other age‐related neurodegenerative diseases like Parkinson's disease (PD), whereby CD38 polymorphisms result in an increased risk of PD development." (PMID 41400119, 2026). "Recent studies have shown that CD38 on Plasma Blast-Plasma cells was associated with a lower risk of Parkinson’s disease, CX3CR1 on CD14- CD16- monocytes was associated with a lower risk of developing cerebral aneurysms and was associated with a higher risk of chronic pancreatitis." (PMID 40328660, 2025). "Further data regarding the effects of Cd38 deletion on dopaminergic neuronal survival are needed to better elucidate the role CD38 may play in neurodegenerative disorders like Parkinson's disease." (PMID 41400119, 2026).
psoriasis (5 papers, 2021 to 2026). An autoimmune condition characterized by red, well-delineated plaques with silvery scales that are usually on the extensor surfaces and scalp. "With regard to genes encoding enzymes involved in NAD+ degradation, increased CD38 transcript levels were observed in psoriasis lesional skin." (PMID 34748530, 2021). "Our data imply that certain B-cell panels, such as CD20−AC, unsw mem %lymphocyte, CD20− %lymphocyte, CD20 on IgD+ CD38−, CD27 on IgD+ CD24+, CD27 on IgD− CD38br, CD27 on IgD− CD38dim, CD38 on naive-mature B cell, and IgD on IgD+ CD38−unsw mem, are related to an elevated risk of psoriasis." (PMID 38558803, 2024). "Exploring activity state of T cells, CD38 and HLA-DR are of particular interest in psoriasis patients." (PMID 37744329, 2023). "Conversely, two traits showed protective connections with psoriasis: sw mem AC (IVW: OR 0.9993, 95% CI 0.9985–1.0000; p = 4.077476e−02), CD19 on IgD+ CD38− unsw mem (IVW: OR 0.9996, 95% CI 0.9992–0.9999; p = 1.260912e−02)." (PMID 38558803, 2024).
pulmonary TB (5 papers, 2010 to 2025). "Side-by-side evaluation of CD27- vs. CD38-based assays to distinguish active from cured TB were previously reported in a pilot study and as a case report in the context of extra-pulmonary TB." (PMID 35492319, 2022). "Furthermore, a comparable level of activation and proliferation markers were found (HLA-DR, CD-38, and Ki-67) between QFT-positive study participants and six months of anti-TB treatment from smear-positive pulmonary TB patients." (PMID 40901996, 2025). "Furthermore, although not statistically significant, the overall magnitude of activation markers (CD-38) from smear-positive pulmonary TB patients was higher than that of smear-negative pulmonary TB patients." (PMID 40901996, 2025). "In the present study antigen specific stimulation profile for activation (HLA-DR, CD-38) and proliferation (KI-67) among pulmonary TB patients (smear positive and smear negative) and comparators (QFT positive, QFT negative, confirmed non TB other respiratory disease) were determined." (PMID 40901996, 2025). "The overall level of activation (HLA-DR, CD-38) and proliferation (Ki-67) markers in the smear-positive and negative pulmonary TB patients was much lower than compared with the healthy QFT positive and negative comparators groups (p-value = 0.0161, p = 0.0171,p = 0.0111, p = 0.034), respectively." (PMID 40901996, 2025). "In addition, the overall magnitude of CD-38 expression was considerably higher in both smear-positive and negative pulmonary TB patients compared with confirmed non-TB other respiratory patients, apparently healthy QFT-positive and negative study participants." (PMID 40901996, 2025). "Also, among the smear-negative pulmonary TB cohort, the expression of CD-38, HLA-DR, and HLA-DR + CD-38 + expression was reduced in the second month and six-month cohort compared with baseline data (p-value= < 0.0001, p-value = 0.00365, p –value = 0.0001, respectively)." (PMID 40901996, 2025). "Also, among the smear-negative and positive pulmonary TB cohort, the expression of CD-38, HLA-DR, and HLA-DR + CD-38 + expression was reduced in the second month and six-month cohort compared with baseline data (p-value= < 0.0001, p-value = 0.00365, p –value = 0.0001, respectively)." (PMID 40901996, 2025).